VWF (von Willebrand factor)
Diseases named in the same sentence as VWF in open-access papers (continued):
Sharing a sentence is not in itself a finding about the gene and the disease.
Stroke (continued). "The von Willebrand factor (vWF) is a key participant in the platelet-dependent thromboinflammation and stroke development." (PMID 34944761, 2021). "ADAMTS13 is a well-described cleaving protease of von Willebrand factor (vWF), a key player in thrombus formation and has been suggested a new therapeutic agent for promoting stroke recovery." (PMID 33930055, 2021). "A recent study focusing on stroke outcomes and prophylactic options in patients with elevated VWF levels showed positive results using the GPIb-VWF blocker caplacizumab to reduce infarct size in pre-clinical studies." (PMID 34184557, 2021). "In a meta-analysis that investigated the association between VWF, ADAMTS13 and cardiovascular outcomes, most of the studies found an increased risk of myocardial infarction or stroke." (PMID 34134634, 2021). "The important role of immune cells on stroke progression is well established, likewise immune cells interact with molecules involved in platelet signaling, such as VWF, contributing to thrombus formation." (PMID 33692737, 2021). "We previously identified von Willebrand factor (VWF) as an important constituent of stroke thrombi, conferring resistance to fibrinolytic therapy in mice." (PMID 33618719, 2021). "Paeoniflorin treatment resulted in a significant upregulation of the vWF expression in peri-infarct zone compared with control in rat stroke model." (PMID 34123580, 2021). "The effect of conventional anti-platelet agents is limited in secondary stroke prevention, and their effects are blunted under high shear stress in the presence of increased levels of circulating von Willebrand factor (VWF)." (PMID 33542410, 2021). "Further, there is also a correlation between the vWF levels and stroke subtypes as well as the functional outcomes in AIS patients." (PMID 33107067, 2021). "In a rat stroke model, M4P co-localized with neuronal marker NeuN and endothelial marker vWF, whereas few GFAP positive astrocytes were stained by M4P in the ipsilateral hemisphere." (PMID 33195194, 2020). "Endothelial cell-derived vWF has also been reported to play a role in thrombosis and proinflammation in stroke and in ischemic injuries." (PMID 31935960, 2020). "In line with our results, numerous studies have reported that ADAMTS13 obviously reduced inflammation in atherosclerosis and stroke via cleaving active VWF." (PMID 32075652, 2020). "Previous report showed that vWF aggravates thrombotic disease such as stroke via a GPIb-dependent mechanism." (PMID 32322295, 2020). "According to the Trial of Org 10172 in Acute Stroke Treatment (TOAST) classification, levels of vWF increase in all types of stroke in its acute phase, although after 3 months its increased concentration remains in the cardioembolic and cryptogenic stroke." (PMID 31701356, 2020). "On these bases, the control of VWF expression has been proposed as an interesting therapeutic tool to treat thrombotic diseases such a stroke and myocardial infarction." (PMID 32231163, 2020). "Given the fundamental role of VWF and GPIbα in thrombus development at sites of vascular damage, it is not surprising that the VWF-GPIbα axis is responsible for thrombotic events in stroke." (PMID 31921147, 2019). "For comparison, at 2 h post-stroke, 50.6 ± 4.1% vWF-positive vessels were co-stained by anti-TRPM4 antibody which increased to 72.6 ± 3.4% by 6 h." (PMID 29569041, 2019). "Initial results indeed indicate that interfering with VWF or GPIb can modulate the cerebrovascular integrity after stroke." (PMID 31921147, 2019). "The clinical significance of the VWF-GPIbα interaction in stroke is suggested by an increasing number of human stroke studies showing the pathophysiological involvement of VWF in ischemic stroke." (PMID 31921147, 2019). "CD69 was identified as a negative regulator of endothelial VWF release, and in the setting of stroke, its absence resulted in a more severe stroke burden due to increased cerebral thrombosis." (PMID 31921147, 2019).
Stroke (continued). "Variable levels of vWF expression have been reported in other vascular insults, like myocardial infarction, cardiac arrest, and stroke." (PMID 30972003, 2019). "A study even showed the correlation between levels of VWF and subtypes of stroke as well as functional outcomes in AIS patients." (PMID 31379722, 2019). "Correspondingly, ADAMTS13 deficient mice showed an increased number of thrombi containing fibrin and VWF in the brain lesions after stroke." (PMID 31921147, 2019). "More research, preferably also in larger animal models, is needed to bring the concept of blocking VWF-mediated thromboinflammation in stroke closer to the clinic." (PMID 31921147, 2019). "Future studies need to define populations that are prone to developing vWF-mediated stroke and identify stroke sub-types that are sensitive to vWF inhibition to further refine the strategy for the clinical development of such agents." (PMID 29847840, 2018). "We still lack confirming data, but given the fact that stroke recurrence is highest shortly after stroke, it would be desirable to gain new data on early stroke recurrence with respect to vWF levels." (PMID 29847840, 2018). "They prospectively determined vWF levels in almost 1,600 stroke-naïve participants at baseline with a follow-up for cardiovascular events after 5 years." (PMID 29847840, 2018). "Evidence for the causative role of vWF in stroke comes from large longitudinal studies that investigated stroke-naïve patients and analysed their stroke prevalence with respect to baseline vWF levels and ADMTS13 activity." (PMID 29847840, 2018). "Animal studies that improved understanding of the impact of vWF on stroke have recently been thoroughly reviewed by Denorme and De Meyer12and thus will not be discussed in detail." (PMID 29847840, 2018). "In patients with cardiovascular disease, including CAD and stroke, VWF and ADAMTS13 are both predictors of future CV events." (PMID 28634421, 2017). "This improvement is at least in part due to the engrafted hUCB MNCs forming new vessels during stroke recovery, as indicated by the engrafted cells showing microvascular-like structure and expressing the endothelial marker vWF." (PMID 28330501, 2017). "An elevated level of vWF predicts the appearance of the first stroke, recurrent myocardial infarction and death in patients with coronary artery disease." (PMID 28570705, 2017). "The plasma level of vWF antigen (vWF-ag) was measured both in the acute phase and in the chronic phase three months after stroke." (PMID 28570705, 2017). "Our results of the elevated level of stable phase vWF in a stroke patients are in line with previous observations of the chronic inflammation/pro-thrombotic tendency in patients with cerebrovascular disease." (PMID 28570705, 2017). "When used in combination with tPA, VWF antagonists were able to prevent ongoing microvascular thrombus formation reducing stroke progression." (PMID 29410644, 2017). "The main result of our study was that in patients with a history of a recent (3 months earlier) stroke, the level of vWF-ag correlated with the areas of visceral and pericardial adipose tissue, but not with its subcutaneous counterpart or BMI." (PMID 28570705, 2017). "The regression model describes the ln-transformed OPG levels as a dependent variable in the whole studied population, and contains gender, age, diagnosis of PAD, stroke history, ln-transformed VWF: CB and 0/non-0 blood group categories." (PMID 27387019, 2016). "Plasma vWF:Ag and D-D concentrations significantly correlated with the National Institute of Health Stroke Scale (NIHSS) scores (r=0.625 and 0.582, respectively; P<0.01)." (PMID 24926346, 2014). "On the other hand, high levels of VWF : Ag are associated with thrombotic risks and had been extensively studied in many medical conditions particularly coronary heart disease (CHD) and stroke." (PMID 25759835, 2014).
Stroke (continued). "In a previous study by our group cardioembolic stroke appears as the “less atherosclerotic” among each diagnostic subtype of stroke, reporting the correlation of PWV only with CRP and vWF." (PMID 24571954, 2014). "In various stroke models, blocking VWF by monoclonal antibodies has been shown to provide an impressive protective effect." (PMID 24937073, 2014). "Von Willebrand Factor (vWF), a well studied hemostatic marker, has been found to be related with CE stroke." (PMID 24527683, 2013). "As authors discussed, these results agree with those from Ohira and colleagues, in which CE stroke patients also showed increased levels of vWF than patients with SVD (p<0.05)." (PMID 24527683, 2013). "Overall, the results suggest that caADAMTS13 may provide improved early thrombolytic properties compared with the standard of care against platelet- and VWF-rich thrombi in a preclinical stroke model." (PMID 40171654, 2025). "Similarly, in the study by Taylor and colleagues, the VWF: Ag/ADAMTS13 activity ratio at stroke presentation correlated with higher modified Rankin scale scores (p = 0.021) and NIHSS scores (p = 0.029) at follow-up." (PMID 40217918, 2025). "Thus, our results showing high content of vWF in clots retrieved from stroke patients with concomitant cancer, lend new and further support to the previous literature suggesting a key role of vWF in the formation of clots in patients with active cancer." (PMID 39760182, 2025). "It is also important to consider that vWF levels may vary significantly at different time points during the course of a stroke, further complicating the interpretation of these results." (PMID 40135640, 2025). "Current research underscores the importance of platelet adhesion and early activation in mediating thromboinflammatory damage post-stroke, primarily through interactions involving glycoprotein (GP) VI and integrin α2β1 with collagen, and GPIbα with von Willebrand factor (VWF)." (PMID 40356948, 2025). "High vWF levels, as seen in stroke and cardiovascular disease, could also be potentially mitigated by recombinant ADAMTS13 more safely than by plasma transfusion, thus showing the potential of this protein in biomedical applications." (PMID 38396603, 2024). "Xiang and colleagues suggest that vWF regulation may serve as a powerful therapeutic target in treating thrombotic diseases such as stroke or myocardial infarction." (PMID 37940678, 2023). "β-TG, VWF, FVIII, fibrinogen, D-dimer, TAFI, and NETs were associated with risk of IS, stroke severity at the acute moment, and clinical outcome after treatment, and for that matter, they may be the most interesting candidates." (PMID 37274178, 2023). "Interestingly, platelet-rich areas in stroke thrombi were accompanied with fibrin rich-structures embedded with VWF, leukocytes and DNA in and around these platelet-rich regions." (PMID 36674781, 2023). "VWF has been shown to play a central role in thrombotic diseases such as stroke." (PMID 35869501, 2022). "In addition, von Willebrand Factor (vWF) and neutrophil extracellular traps are found in varying amounts in the majority of stroke thrombi." (PMID 35665052, 2022). "Interestingly, levels of vWF and Factor VIII are directly linked to the severity of thrombosis and the ensuing stroke." (PMID 33562030, 2021). "A third generation anti-VWF aptamer (BT200) has been generated which could be useful for secondary stroke prevention." (PMID 33542410, 2021). "Therefore, several clinical studies have utilized strategies to inhibit vWF or enhance ADAMSTS13 in the management of stroke, including in knockout transgenic animals." (PMID 34944761, 2021). "We also suggest that ADAMTS13 could be targeted to promote cleaving of vWF, thereby preventing thrombus formation and subsequent stroke." (PMID 33930055, 2021).
Stroke (continued). "Patients with average VWF plasma levels of 24% had a 35–67% reduced risk for ischemic stroke as compared to controls, suggesting that partial inhibition of VWF could be protective in the stroke-prone population." (PMID 33542410, 2021). "Finally, there is clear evidence that elevated levels of vWF are a predictive factor for ischemic heart disease, cardiovascular mortality and stroke in healthy individuals, and iCAM for myocardial infarction." (PMID 32537688, 2020). "Accordingly, inhibition of phospholipases D1 and D2, which are downstream signals of the vWF‐GPIb axis in platelets, has yielded reduced susceptibility to stroke progression following tMCAO again without increasing bleeding risk." (PMID 33123127, 2020). "VWF deregulation is increasingly correlated with a higher incidence of heart attack and stroke." (PMID 32231163, 2020). "In view of the delineated GPIb-mediated interaction between platelets and leukocytes, the vWF/GPIb axis could, however, be a potential pathomechanism of thromboinflammation in stroke." (PMID 33123127, 2020). "Moreover, the CEI group displayed also slightly increased plasma levels of von Willebrand factor (vWF) compared to the rest of the stroke groups." (PMID 32899616, 2020). "Also, the potential effect of VWF and platelets on vascular permeability in the stroke brain needs further study." (PMID 31921147, 2019). "However, many aspects of the spatiotemporal involvement and molecular interactions between VWF and leukocytes in stroke remain to be elucidated." (PMID 31921147, 2019). "Collectively, these studies argue for the GPIb-vWF axis as an attractive target for stroke therapy." (PMID 31736950, 2019). "Furthermore, degradation of tight junctions in the area surrounding the photothrombotic stroke was accompanied by the activation of endothelial cells, as indicated by a massive release of vWF." (PMID 31430854, 2019). "We have previously shown that low activity of ADAMTS13 itself is associated with increased risk of cardiovascular disease, while the combination of VWF and ADAMTS13 appears indeed more strongly associated with stroke risk than what would be expected on the basis of the individual measurements." (PMID 29615758, 2018). "Immunohistochemistry revealed EPC activation and localization and enhanced vascularization in G-CSF-treated animals, as demonstrated by increased levels of EPC and vasculogenesis markers, CD34+ and VEGFR-2 and vWF, respectively, in the ipsilateral cortex and striatum of stroke animals." (PMID 29857523, 2018). "Therapeutic inhibition of VWF by novel agents appears particularly promising for secondary prevention of stroke recurrence in specific sub-groups of patients such as those suffering from large artery atherosclerosis, as designated according to the TOAST classification." (PMID 29847840, 2018). "However, when interpreting results from stroke studies investigating vWF levels, disadvantages of the used methods need to be taken into account for the distinct method." (PMID 29847840, 2018). "The increased vWF expression in the ischemic cortex and striatum of G-CSF-treated rats 3 and 7 days after stroke suggest enhanced vascularization in these brain regions, which could explain the motor and functional recovery in these animals." (PMID 29857523, 2018). "The rationale for vWF as a potential target in stroke comes from four bodies of evidence." (PMID 29847840, 2018). "In the Rotterdam Study, which included more than 6000 participants, the risk of stroke was associated with vWF levels in the general population, no matter AF was present or not34." (PMID 28134282, 2017). "Here, we hypothesized that levels of FVIII and VWF are related to stroke severity and/or patient outcome following thrombolysis treatment." (PMID 29410644, 2017).
Stroke (continued). "Given the potential role of ADAMTS13 and VWF in stroke progression and severity, we correlated the levels of ADAMTS13 and the VWF:ADAMTS13 ratios in AIS and TIA patients on day 0 with key demographic and clinical parameters by univariate and multivariate analysis." (PMID 28591212, 2017). "The role of VWF in stroke has been diffusely investigated in animal models." (PMID 28634421, 2017). "FVIII activity and VWF antigen levels according to stroke severity on admission." (PMID 29410644, 2017). "vWF is a specific marker for endothelial cells, and evidence from animal models reveals that the number of vWF+ blood vessels increases in the peri-infarct area after stroke." (PMID 29017609, 2017). "In individuals without SCD, elevated vWF levels have been associated with increased risk for stroke, as both acute stroke patients and those with carotid atherosclerosis had elevated blood levels compared to healthy controls." (PMID 26305570, 2015). "Age, sex, and stroke severity influenced VWF levels (P<0.05)." (PMID 24937073, 2014). "Thus, targeting VWF-mediated platelet adhesion and activation is now considered as a potential target for stroke prevention and acute stroke treatment." (PMID 24937073, 2014). "The greater mortality associated with sarcopenia and sarcopenic obesity (but not obesity) remained after adjustment for prevalent MI, prevalent stroke, HDL-C, SBP, FEV1, CRP, D-dimer, vWF, and weight loss (sarcopenic, HR = 1.34, 95% CI = 1.15–1.57; sarcopenic obese, HR = 1.44, 95% CI = 1.10–1.90)." (PMID 24428349, 2014). "However, the situation remains complex as others found a marked reduction of VWF –mediated platelet adhesion and marked reduction of cerebral infarct volume in a similar mouse stroke model with GPIIb knockout." (PMID 23935828, 2013). "Because it is a strong predictor of higher vWF blood levels, higher periatrial EAT might also be associated with higher stroke incidence in patients with AF." (PMID 24143210, 2013). "GPVI-mediated and von Willebrand Factor (vWF)-mediated platelet adhesion and activation play an important role in thrombus formation and subsequent development of stroke and could be a target for pharmacological inhibition of pathological thrombus formation." (PMID 23935828, 2013). "Since an increasing amount of evidence suggests that GPIbα and VWF could also mediate inflammatory processes, further studies are needed to establish whether inhibition of these molecules also reduce inflammation in stroke." (PMID 21914206, 2011). "As continuous variables, IL-6 (p = 0.02), CRP (p = 0.03), MMP-9 (p = 0.004), D-dimer (p < 0.001), LDL (p = 0.03), von Willebrand factor (p = 0.10), and factor VIII activity (p = 0.10) were positively associated with stroke, whereas HDL-3 was inversely associated (p = 0.02) with stroke." (PMID 17571161, 2007). "Furthermore, in the Stroke + Kr group, the vWF was equally detected in the penumbra and lesion, which may indicate active neoangiogenesis in the lesion zone compared with that in the control group, in which the vWF was predominantly detected in the penumbra." (PMID 38540249, 2024). "In addition, increased NETs, as well as fibrin and von Willebrand Factor (vWF) composition in thrombi, might reduce the likelihood of revascularization by altering thrombus mechanical properties in patients with stroke." (PMID 38188146, 2024). "Studies in mice demonstrated that GPIbα is an important mediator of ischemic stroke, suggesting that targeted inhibition of this receptor may open new approaches for stroke treatment, especially in view of the thromboinflammatory axis played by VWF-GPIbα interaction in acute ischemic stroke." (PMID 35518205, 2022). "Previous studies have demonstrated that miR-100 downregulation could be related to an increase in VWF and that miR-100 could be involved in both enhancing new vessel formation and in vascular remodelling after stroke in mice, thereby promoting recovery in patients with CSC stroke." (PMID 34356850, 2021).